PLOD3 (procollagen-lysine,2-oxoglutarate 5-dioxygenase 3)
Diseases named in the same sentence as PLOD3 in open-access papers (continued):
Sharing a sentence is not in itself a finding about the gene and the disease.
liver cancer (3 papers, 2020 to 2024). An epithelial or non-epithelial malignant neoplasm that arises from the liver. "Overall, this evidence suggests that the knockdown of PLOD3 dramatically decreases liver cancer colonies in vivo and preserves liver function." (PMID 38184566, 2024). "According to the ONCOMINE data, the hepatic expression levels of PLOD2 and PLOD3 were remarkably elevated in liver cancer tissue compared to normal liver tissue." (PMID 33014843, 2020). "Increased collagen deposition and cross-linking may promote cancer development and progression by promoting the invasion, migration, and proliferation of cancer cells, An animal model of spontaneous liver cancer has been reported to suppress liver tumor incidence through knockdown of PLOD3." (PMID 35835735, 2022).
lung adenocarcinoma (3 papers, 2018 to 2021). A carcinoma that arises from the lung and is characterized by the presence of malignant glandular epithelial cells. "Accordingly, depletion of PAQR11 in human lung adenocarcinoma cells reduced the secretion of proteins - such as the collagen-modifying enzyme procollagen-lysine,2-oxoglutarate 5-dioxygenase 3 (PLOD3) – that were enriched in Gene Ontology terms, “ECM degradation,” and “proteolysis regulation”." (PMID 34957124, 2021).
pancreatic cancers (3 papers, 2018 to 2021). "Recently, PLOD3 overexpression has been found in gastric, colorectal, and pancreatic cancers." (PMID 29644003, 2018). "Moreover, PLOD3 overexpression has been reported in gastric, colorectal, and pancreatic cancers and glioma." (PMID 30442941, 2018). "Moreover, PLOD3 overexpression is found in gastric, colorectal, and pancreatic cancers." (PMID 29644003, 2018).
arthrogryposis (2 papers, 2019 to 2023). A rare, non-progressive congenital disorder characterized by multiple joint contractures which are present at birth. "Although arthrogryposis can result from the incorrect trafficking of LH3 by CHEVI, mutations in PLOD3 itself, the gene that encodes LH3, can also result in an arthrogryposis phenotype without affecting the CHEVI complex." (PMID 37686358, 2023).
brain tumor (2 papers, 2018 to 2021). "Under the assumption that high-grade brain tumors overexpress PLOD3, we analyzed the Gene Expression Omnibus (GEO) profile dataset and found that PLOD3 expression was positively correlated with WHO grading." (PMID 29644003, 2018).
cerebral small vessel disease (2 papers, 2022 to 2024). Cerebral small vessel disease is the term currently used to pathological processes that affect the brain parenchymal circulation (arterioles, capillaries, and veins). "Recently, a homozygous PLOD3 small inframe deletion was shown to cause a cerebral small vessel disease characterized by multiple white matter hypersignals and bleeding foci in an infant with a few dysmorphic features." (PMID 36403858, 2022).
colon cancer (2 papers, 2021 to 2024). "This study revealed the essential biological functions of PLOD3 in colon cancer progression and metastasis, suggesting that PLOD3 is a promising translational medicine target and bioengineering targeting PLOD3 overcomes CRC liver metastasis." (PMID 38184566, 2024). "Notably, TGF-beta signaling in EMT is a key player in angiogenesis, tumor growth, and metastasis in colon cancer, suggesting that PLOD3 might regulate immune microenvironment of COAD via TGF-beta signaling." (PMID 34239923, 2021). "Therefore, PLOD3 may participate in colon cancer and liver metastasis." (PMID 38184566, 2024). "To further understand the effects of PLOD3 on CRC liver metastasis, we detected the activation status of peripheral blood CD8+ T cells in mice with colon cancer liver metastases by flow cytometry." (PMID 38184566, 2024).
epidermolysis bullosa (2 papers, 2022 to 2023). Epidermolysis bullosa (EB) is a group of genetic skin diseases that cause the skin to blister very easily. "Previously identified pathogenic PLOD3 missense variants cause phenotypically overlapping connective disorders including Stickler-like syndrome and epidermolysis bullosa." (PMID 36403858, 2022). "An example being LH3, encoded by procollagen-lysine, 2-oxoglutarate 5-dioxygenase 3 (PLOD3), whereby pathogenic variants cause connective tissue phenotypes that overlap with Stickler-like syndrome and epidermolysis bullosa." (PMID 36403858, 2022). "Interestingly, in addition to clinical manifestations overlapping Stickler-like syndrome and epidermolysis bullosa, cerebral hemorrhages have been reported in three cases with PLOD3 variants." (PMID 36403858, 2022).
infertile (2 papers, 2020 to 2023). "In the present study ourcandidate genes, AKAP3 and PLOD3 were selected aftersequencing analysis and these mutations further characterized translational event after using bioinformatics toolsin the case of infertility." (PMID 32681621, 2020). "Another relevant PLOD3 gene associated to infertility is a memberof family of lysyl hydroxylase that catalyses hydroxylation of proline and lysine at the time of collagen synthesis." (PMID 32681621, 2020). "The present study explores acquaintance betweenchanges of nucleotides (frameshift and non-frameshiftmutation) in AKAP3 and PLOD3 gene and their transcriptional events (amino acids) in the cases of infertility." (PMID 32681621, 2020).
osteosarcoma (2 papers, 2020 to 2023). A usually aggressive malignant bone-forming mesenchymal neoplasm, predominantly affecting adolescents and young adults. "In our study, PLOD1 expression, not PLOD2 and PLOD3 expression, increased in osteosarcoma tissues compared with normal tissues." (PMID 33134376, 2020). "We found that PLOD1 was upregulated in osteosarcoma tissues when compared with normal bone tissues in GSE16088 and GSE33382, while the expression pattern of PLOD2 and PLOD3 was not consistent in two public datasets." (PMID 33134376, 2020). "Results of RT-PCR in 56 osteosarcoma tissues revealed that expression of PLOD1 was higher in patients with lung metastasis presented at diagnosis than those without metastasis (P < 0.01), while PLOD2 and PLOD3 expression presented no significance between two groups (all P > 0.05)." (PMID 33134376, 2020).
Parkinson disease (2 papers, 2023). A progressive degenerative disorder of the central nervous system characterized by loss of dopamine producing neurons in the substantia nigra and the presence of Lewy bodies in the substantia nigra and locus coeruleus. "In the GSE49036 dataset consisting of patients with Parkinson’s disease at different Braak stages, there was significant difference in the expression of EN1, PLOD3 and LOXL1 in the different Braak stages 0 to 6 of Parkinson’s disease." (PMID 36825022, 2023).
recessive dystrophic epidermolysis bullosa (2 papers, 2015 to 2018). "The reduction of PLOD3 protein at the basement membrane is associated with recessive dystrophic epidermolysis bullosa (RDEB) progression." (PMID 30003082, 2018).
adenoma (1 paper, 2021). A neoplasm arising from the epithelium. "PLOD3 was identified as a key protein associated with the malignant potential of TVA and promoted the viability of adenoma organoids." (PMID 34585630, 2021). "The functional experiments indicated that PLOD3 promotes the viability and proliferation of adenoma." (PMID 34585630, 2021). "At the adenoma organoid level, we found that PLOD3 can promote the viability and proliferation of adenoma." (PMID 34585630, 2021). "After confirming the knockdown ability of si-RNA-mediated knockdown of PLOD3 in adenoma organoids generated from fresh surgical specimens, we investigated its effects on viability." (PMID 34585630, 2021). "Besides the function of PLOD3 at the adenoma level, we also found that PLOD3 is upregulated in tumor tissue." (PMID 34585630, 2021). "The function of PLOD3 was validated using adenoma organoids." (PMID 34585630, 2021). "Then we identified PLOD3 as the potential malignant predictive protein of TVA and validated the function of PLOD3 on adenoma organoids." (PMID 34585630, 2021).
advanced heart failure (1 paper, 2023). Patients with advanced heart failure have severe limitations, experiences symptoms even while at rest and are mostly bedbound patients. "Study investigators encountered a female Becker muscular dystrophy (BMD) carrier with advanced heart failure (HF) and identified a stop-gain variant in procollagen-lysine, 2-oxoglutarate 5-dioxygenase 3 (PLOD3) as a potential second-hit variant." (PMID 37426526, 2023).
amoebiasis (1 paper, 2021). "The functional annotations of PLOD2 and PLOD3 were protein digestion and absorption, amoebiasis, and AGE-RAGE signaling pathways in diabetic complications." (PMID 35265665, 2021). "Functional annotations of PLOD2 and PLOD3 indicated that they are involved in protein digestion and absorption, amoebiasis, and AGE-RAGE signaling pathways in diabetic complications." (PMID 35265665, 2021).
arterial hypertension (1 paper, 2024). "It is worth noting that in our study, patient #54 with three VUSs (in genes FBN1, COL3A1, and PLOD3) has only one CVD risk factor: arterial hypertension." (PMID 39125885, 2024).
colitis (1 paper, 2025). Inflammation of the colon. "In conclusion, our study suggested that targeting PLOD3 may be a potential therapeutic strategy for preventing CRC initiation in a colitis-associated setting." (PMID 40133271, 2025).
Dry skin (1 paper, 2023). Skin characterized by the lack of natural or normal moisture. "It is interesting, that most disorders have additional skin manifestations such as dry skin in both ARC syndrome and collagen VI disorders, and fragile skin in patients with PLOD2, FKBP10 and PLOD3 mutations." (PMID 37686358, 2023).
esophageal squamous cell carcinoma (1 paper, 2025). Esophageal squamous cell carcinoma (ESCC) is a type of esophageal carcinoma (EC) that can affect any part of the esophagus, but is usually located in the upper or middle third. "RBM15 also modulates procollagen-lysine,2-oxoglutarate 5-dioxygenase 3 (PLOD3), enhancing tumor-infiltrating CD4+ T cell abundance in esophageal squamous cell carcinoma (ESCC), correlating with favorable prognosis in ESCC4." (PMID 40370450, 2025).
Gould syndrome (1 paper, 2022). "LH3 is proposed to have substrate preference for heavily glycosylated collagens such as type IV collagen, raising the possibility that PLOD3 pathogenic variants could also cause Gould syndrome." (PMID 36403858, 2022). "Furthermore, since perinatal cerebral hemorrhage is a cardinal feature of Gould syndrome, we performed a genetic screen for PLOD3 variants in a fetal stroke cohort that was negative for COL4A1 and COL4A2 pathogenic variants." (PMID 36403858, 2022).
kidney cancer (1 paper, 2019). Primary or metastatic malignant neoplasm involving the kidney. "Analysis of PLOD1, PLOD2, and PLOD3 mRNA expression in 20 cancer types (Oncomine dataset) showed significant upregulation and downregulation of the three PLOD isoforms in a number of cancers, including kidney cancer, compared with the corresponding normal tissues." (PMID 31446433, 2019).
lymph node metastasis (1 paper, 2025). "This association becomes particularly evident when analyzing specific clinical subgroups, N1 + N2 group with lymph node metastasis, M1 group with distant metastasis, and III + IV tumor stage group all exhibited significantly greater levels of PLOD3 expression." (PMID 40133271, 2025).
melanoma (1 paper, 2021). A malignant, usually aggressive tumor composed of atypical, neoplastic melanocytes. "Consistently, the dysregulation of PLOD3 by aberrant DNA methylation has been found in melanoma." (PMID 34239923, 2021).
prostate carcinoma (1 paper, 2021). A carcinoma that arises from epithelial cells of the prostate gland. "Procollagen-lysine, 2-oxoglutarate 5-dioxygenase 3 (PLOD3) expression was found to be correlated to the progression and migration of cancer cells in gastric, lung and prostate cancer." (PMID 34576068, 2021).
renal carcinoma (1 paper, 2021). A carcinoma arising from the epithelium of the renal parenchyma or the renal pelvis. "PLOD3 knockdown suppresses the malignant progression of renal carcinoma." (PMID 34421605, 2021).
scleroderma (1 paper, 2022). Scleroderma is a rare autoimmune connective tissue disorder characterized by abnormal hardening of the skin and, sometimes, other organs. "In contrast to the untreated scleroderma mice group, the ability of endothelial development associated proteins (LAMC2, PLOD3, and TP63) recovered in the treatment group." (PMID 35315234, 2022).
small cell lung carcinoma (1 paper, 2021). Small cell lung cancer (SCLC) is a highly aggressive malignant neoplasm, accounting for 10-15% of lung cancer cases, characterized byrapid growth, and early metastasis. "Kyoto Encyclopedia of Genes and Genomes (KEGG) pathway analysis shows that the expression of PLOD3 is associated with many factors, and the PLOD3 gene could be involved in oncogenesis and cancers metastasis by “protein digestion and absorption”, “focal adhesion” and “small cell lung cancer”." (PMID 34576068, 2021).
squamous cell carcinoma (1 paper, 2018). A carcinoma arising from squamous epithelial cells. "Furthermore, PLOD3 was upregulated in 37 squamous cell carcinoma patients, 15 adenocarcinoma patients, and 7 others compared to that in the corresponding tumors from the same patients." (PMID 30442941, 2018).
triple-negative breast carcinoma (1 paper, 2024). An invasive breast carcinoma which is negative for expression of estrogen receptor (ER), progesterone receptor (PR), and human epidermal growth factor receptor 2 (HER2). "Besides, the levels of PLOD1, PLOD2 and PLOD3 were higher in triple negative breast cancer (TNBC) patients than non-TNBC patients." (PMID 39068670, 2024).
cancer (31 papers, 2016 to 2025). A tumor composed of atypical neoplastic, often pleomorphic cells that invade other tissues. "PLOD3 overexpression is correlated with high circulating protein levels in some patients and increasing evidence suggested that PLOD3 is associated with tumorigenesis in various cancer types." (PMID 34646265, 2021). "As genome instability is a hallmark of cancer, we then investigated the association between PLOD3 and genomic instability such as chromosomal instability (CIN) and microsatellite instability (MSI) in COAD." (PMID 34239923, 2021). "A high expression of PLOD3 was associated with poor OS in some cancers, namely, in ACC, CESC, LGG, LIHC, MESO and UVM (all p < 0.05)." (PMID 34576068, 2021). "The heatmap shows correlations between PLOD3 expression and cancer associated fibroblasts (CAF) across diverse cancers of TCGA database." (PMID 34576068, 2021). "In this study, PLOD3 amplification is underrepresented in cancers such as UCEC and SKCM, while mutations occur most often (7.94% and 3.9%)." (PMID 34576068, 2021). "Taken together, these results suggest that PLOD3 status is strongly associated with cancer cell chemosensitivity." (PMID 30770789, 2019). "Emerging evidence suggests that PLOD3 is associated with tumorigenesis in various cancer types." (PMID 34239923, 2021). "Therefore, understanding the mechanisms resulting in PLOD3 mutation, as well as its biological effects, might affect the diagnosis and therapy of cancer." (PMID 34576068, 2021). "Interestingly, several of the proteins that exhibited alterations in N-glycoprotein expression levels (e.g., EGFR (epidermal growth factor receptor), LGALS3BP (Galectin-3-binding protein) and PLOD3 (Procollagen-lysine, 2-oxoglutarate 5-dioxygenase 3)) in hiPSCs are linked with cancer." (PMID 27808266, 2016). "To further investigate the underlying mechanisms, we examined PLOD3’s role in epithelial-mesenchymal transition (EMT), a fundamental process in cancer metastasis." (PMID 41142622, 2025). "Given its potential significance in cancer progression, further investigation into the function of PLOD3 in CRC is warranted." (PMID 40133271, 2025). "Given that PLOD3 is the sole isozyme crucial for collagen synthesis and maturation, its procancer role has been established in several types of cancer; however, the precise function and mechanism of PLOD3 in CRC remain incompletely understood." (PMID 40133271, 2025). "Numerous studies have highlighted the significant role of PLOD3 in the progression of various cancers." (PMID 40133271, 2025). "We analyzed the mRNA expressions of PLOD1, PLOD2, and PLOD3 in various cancer and normal tissues using Oncomine database." (PMID 39068670, 2024). "Overexpression of PLOD3 were detected in many human diseases, including collagen-related diseases and cancers." (PMID 37258507, 2023). "STAB1, EIF4G1, and PLOD3 have been reported to regulate the proliferation, migration, and invasion of cancer cells; however, the role of FAM208A in cancer is unclear." (PMID 37373553, 2023). "In detail, both ADAM12 and MMP1 expression were upregulated in 16 cancer types (p < 0.05), PLOD3 was upregulated in 17 cancer types (p < 0.05)." (PMID 34121340, 2021). "Some other studies show that CAFs play a role in the process of cancer metastasis and related PLOD3 to metastasis in LUAD." (PMID 34576068, 2021). "In most of the analyzed cancers, PLOD3 gene expression was significantly higher in tissues of cancer compared to its expression in healthy tissues." (PMID 34576068, 2021). "The expression of PLOD3 is positively related to CAF for most of the mentioned cancers, such as BLCA, SARC and CESC." (PMID 34576068, 2021). "Accumulating evidence has implicated members of the procollagen-lysine, 2-oxoglutarate 5-dioxygenase (PLOD) gene family, PLOD1, PLOD2, and PLOD3, in cancer progression and metastasis." (PMID 35265665, 2021).